TNF (tumor necrosis factor)
Diseases named in the same sentence as TNF in open-access papers (continued):
Sharing a sentence is not in itself a finding about the gene and the disease.
Stroke (continued). "This may have significant implications for the development of future neuroprotective treatment strategies in the acute phase after stroke, as modulating the microglial TNF response acutely can provide a viable option to boost neuroprotection." (PMID 27384243, 2016). "Furthermore, in the post-stroke phase, melanocortins regulate the cholinergic anti-inflammatory pathway and downregulate TNF-α." (PMID 27923376, 2016). "IL-1β and TNF-α dramatically affect infarct evolution in experimental stroke models." (PMID 27544687, 2016). "Our findings on expression of TNF and its receptors in brain specimens from stroke patients are in line with previous reports (reviewed in2) and underscore this study’s translational relevance of TNF signaling in human stroke pathology, not only in experimental models." (PMID 27384243, 2016). "In addition, IL1A, IL6, TNF and other anti-stroke targets were also presented an up-regulated trend." (PMID 27672514, 2016). "Interestingly, we found a positive correlation between TNF expression levels and phagocytic activity of microglia after stroke." (PMID 26022493, 2015). "Our finding that microglia produced higher levels of ROS and TNF after stroke than monocytes suggest that the resident cells may be the more detrimental macrophage early after injury." (PMID 26022493, 2015). "TNF-α is believed to play a detrimental role in ischemic injury, since its neutralization with specific monoclonal antibodies or binding proteins provides neuroprotection in experimental stroke models." (PMID 25972779, 2015). "Moreover, up-regulation of TNFα expression following stroke has been shown to decrease SVZ progenitor proliferation, whereas blockade of TNF receptor-1 signaling has been demonstrated to increase stroke-induced SVZ cell proliferation and neuroblast formation." (PMID 26696816, 2015). "Anti-TNF alpha trials demonstrate improved clinical outcomes in experimental and human stroke." (PMID 26664821, 2015). "We have noted that Npas4−/− mice had both increased IL-6 and TNF-α expression post-stroke." (PMID 26690124, 2015). "TNF and IL-1β are produced by both microglia and monocytes after stroke." (PMID 26022493, 2015). "Moreover, a positive correlation was found between the level of TNF production and the number of beads phagocytosed by microglia after stroke (p = 0.0167)." (PMID 26022493, 2015). "We report that local increases in S1P within the brain potentiate damage produced by transient focal cerebral ischemia (M/R), which may represent a new model for recurrent stroke, particularly in view of the effects on markers like TNF-α." (PMID 26576074, 2015). "It was shown that intravenous administration of NSCs reduced OX-42+ microglia and MPO+ neutrophil infiltration into brain lesion and also attenuated both cerebral and splenic activations of TNF-a, IL-6, and NF-kB, which promoted neuroprotection in rat stroke model." (PMID 24719869, 2014). "Therefore, we measured serum levels of IL-6 and TNFα in CaMKK β and CaMK IV KO mice 72 hours after stroke." (PMID 25331941, 2014). "Although we were not able to investigate different pathophysiological mechanisms directly by surrogate markers such as cytokines or tumor necrosis factor alpha or by different cerebral activation patterns, the intention of our study was to compare motor fatigue in patients with stroke and MS." (PMID 25566183, 2014). "For instance, compensation in stroke patients may be enhanced by training, and electric failure in MS lesions may be ameliorated by substances such as 4-aminopyridine or inhibitors of TNF-α." (PMID 25566183, 2014). "Finally, we demonstrated that the levels of the pro-inflammatory serum cytokines TNFα and IL-6 increased after stroke in both CaMKK β and CaMK IV KO mice, indicating that inhibiting this pathway exacerbates the inflammatory response." (PMID 25331941, 2014). "Levels of mRNA coding for CD45, TNFα and IL1β were elevated at 7 and 14 d after stroke." (PMID 25341035, 2014).
Stroke (continued). "Finally, inhibiting this pathway exacerbated the inflammatory response to stroke as CaMKK β or CaMK IV KO mice had increased levels of the pro-inflammatory serum cytokines tumor necrosis factor alpha (TNFα) and interleukin 6 (IL-6) after stroke." (PMID 25331941, 2014). "Inhibition of TNF-α reduces ischemic brain injury, while administration of recombinant TNF-α protein after stroke onset worsens ischemic brain injury, although under certain circumstances TNF-α may be neuroprotective." (PMID 25424430, 2014). "In addition to these observations, pentoxifylline, an anti-inflammatory agent, attenuated damage of stroke via the dual role of TNF-α." (PMID 23431245, 2013). "One possibility was that severe stroke might possibly induce mild release of IFN-γand TNF-α from CD8+ lymphocytes, needs further investigation." (PMID 23286717, 2013). "Inflammatory cytokines, such as IL-1β, IL-6, and TNF-α, are secreted by activated microglial cells and macrophages in stroke lesions and induce the expression of chemokines, which recruit more circulating monocytes/macrophages into lesions and lead to further brain damage." (PMID 23431245, 2013). "Interleukin-1β (IL-1β) and tumor necrosis factor-α (TNF-α) serve as major regulators of immune and inflammatory responses in the CNS, and elevated expression of these cytokines occurs in injury, infection, stroke, inflammation and degenerative disorders such as AD." (PMID 23844119, 2013). "Therefore, agents with the ability to inhibit TNF-α expression are potentially beneficial in the treatment of stroke." (PMID 24285977, 2013). "Further studies are required to clarify the role of TNF-α in stroke." (PMID 23431245, 2013). "However, in the sub-acute phase (7 d reperfusion) following stroke, TREM2-KO mice showed a decreased transcription of pro-inflammatory cytokines TNFα, IL-1α and IL-1β, associated with a reduced microglial activity (CD68, Iba1)." (PMID 23301011, 2013). "To conclude, this may be the first systematic and comprehensive analysis of TNF-α and stroke especially in an Asian population." (PMID 23050663, 2012). "Furthermore, TNF-α, IL-1β, IL-1α, and Cox-2 are well-studied cytokines related to inflammatory responses in stroke, and both appear to exacerbate ischemic damage." (PMID 22719787, 2012). "In an animal model of stroke, administering CpG ODN 3 days before the onset of brain ischemia significantly reduced infarct size and this neuroprotective effect was associated with CpG-induced TNF-α and type I interferon production." (PMID 22708497, 2012). "Moreover, microglia in the hippocampus of rats subjected to stroke were found to specifically express neuroprotective TNFα." (PMID 22293457, 2012). "Indeed, LPS-induced preconditioning in a rat model of stroke required upregulated TNFα and neuroprotective molecules." (PMID 22615780, 2012). "IL-1β may be a more important target for prevention or treatment of stroke when compared with IL-6 and TNF-α." (PMID 23326018, 2012). "Recently, several GWASs for stroke have been reported, but most of these study populations were of European origin and they did not detect the association of rs1800629 in TNF-α with stroke." (PMID 23050663, 2012). "Our results strongly support the involvement of TNF-α in the pathogenesis of stroke, and may have potentially important scientific, clinical, and public health implications." (PMID 23050663, 2012). "Previous experimental studies showed a plateau in expression of ICAM-1 by endothelial cells after TNF-α activation between days 1-3, and after the stroke onset a persistency in soluble ICAM-1 levels on days 1, 3 and 14 was detected; our follow-up data on day 3 is in line with these findings." (PMID 21871109, 2011). "Increased expression of TNF-α has been demonstrated in experimentally induced stroke models." (PMID 22132330, 2011).
Stroke (continued). "As a TIA is a much milder form of stroke, it is possible that the lower levels of TNF-α produced during a TIA contribute to induction of neuroprotective mechanisms, while more pathophysiological levels of TNF-α reached during stroke, exacerbate glutamate-mediated excitotoxicity and cell death." (PMID 21810263, 2011). "In stroke patients, increased cerebrospinal fluid and/or circulating IL-1β, IL-6, IL-10, and CXCL-1 (CINC-1/IL-8), monocyte chemoattractant protein-1, and TNF-α concentrations have been reported, and IL-6 in particular identified as a predictor of stroke outcome." (PMID 21714902, 2011). "Therefore, we were interested the expression of ICAM-1, MCP-1, and VCAM-1 in the astrocytes of SHRSP/IZM rats during stroke statuses such as H/R and TNF-α stimulation." (PMID 20700422, 2010). "Predictors of adverse stroke outcome include TNF-α, ICAM-1, and IL-6." (PMID 20700422, 2010). "Pro-inflammatory cytokines such as IL-1β and TNF-α have been proposed as potent mediators of neuronal death in several neurodegenerative diseases like AD, traumatic brain injury, epilepsy, Parkinson's disease, stroke, HIV and JE." (PMID 21034511, 2010). "Increased serum TNF-α, one of the main proinflammatory cytokines regulating an inflammatory response, has been demonstrated to be associated with increased mortality rate of SICH and recurrent stroke." (PMID 20534169, 2010). "Tumor necrosis factor α (TNF-α) is interesting in the context of retinal circulatory failure in that it is involved in mediating the harmful processes that are initiated following stroke and ischemic heart disease." (PMID 21152396, 2010). "The increases in ICAM-1 and VCAM-1 after stroke are influenced by IL-1β and TNF-α." (PMID 21040547, 2010). "Our overall goal in performing this work was to determine how elevated levels of TNFα protein, such as may be observed in human brain after stroke, will modify cerebral ischemic injury." (PMID 18947406, 2008). "A more robust relationship between sTNF-RI and stroke severity or outcome may reflect a longer half-life of receptors compared to TNF-α." (PMID 17328808, 2007). "Despite its established pathogenic role, TNF-α has not become a clinical target in stroke therapy." (PMID 40869247, 2025). "The DEGs were also related to signaling pathways such as the TNF signaling pathway that contributes to neuroinflammatory injury in ICH, and are associated with diseases such as Type I diabetes mellitus, which is closely linked with the increased risk of cardiovascular events, including stroke." (PMID 40933575, 2025). "Notably, pro-inflammatory responses are not exclusive to post-stroke pathology but are also a hallmark of depression, with elevated levels of cytokines such as IL-6 and TNF-α observed in depressive patients." (PMID 40144659, 2025). "Additionally, persistently high levels of TNF-α (above 24 pg/mL) and sTWEAK (above 7000 pg/mL) were linked to a 2-fold and 5-fold increased risk of atherothrombotic and intracerebral hemorrhage (ICH) stroke recurrences, respectively." (PMID 40094903, 2025). "First, after a stroke occurs, ischemia and hypoxia in the damaged brain tissue trigger an inflammatory cascade reaction, inducing infiltration of circulating immune-inflammatory cells (such as neutrophils and monocytes) and inflammatory mediators (such as TNF-α) into the local tissues." (PMID 40901663, 2025). "Therefore, the detection and targeted intervention of concentrations of IL-1β, IL-6 and TNF-α post-stroke may contribute to the diagnosis and treatment of PSD." (PMID 38377025, 2024). "Frail patients have been shown to have elevated inflammatory markers, including C-reactive protein, IL-6, and TNF-α, and elevated levels of Factor VIII and D-dimer, which raise concern for an underlying coagulopathic state which may predispose them to stroke and myocardial infarction." (PMID 38276658, 2024).
Stroke (continued). "Under pathological conditions such as stroke, astrocytes become reactive, markedly increasing the expression of glial fibrillary acidic protein (GFAP), the hallmark signature of reactive gliosis, in response to intercellular signaling molecules including IL-6, TNFα, TGF-β, INFγ, and IL-10." (PMID 38854014, 2024). "In addition, butyric acid could inhibit the activation of the microglia and astrocytes in the brains of model mice, thereby inhibiting the generation of pro-inflammatory factors IL-6, IL-1β and TNF-α as well as improving stroke outcomes." (PMID 38201839, 2023). "Furthermore, plasma TNF-α levels were elevated in stroke patients compared to healthy controls." (PMID 36769472, 2023). "Therefore, one possible mechanism to decrease post-stroke pain is decreasing TNF alpha." (PMID 37065345, 2023). "Neutrophils are attracted to the ischemic tissue after stroke and activated by tumor necrosis factor-α (TNF-α), interleukin-1β (IL-1β), and interleukin-8 (IL-8) secreted by microglia or astrocytes, followed by the release of NETs, which may inversely activate glial cells and lead to neuronal damage." (PMID 36892020, 2023). "A rise in TNF-α is one of the earliest events to occur as part of an inflammatory response to ischemic brain damage, peaking between 12–24 h and contributing to triggering the cascade of other inflammatory components in blood, brain and CSF in stroke animal models." (PMID 35631536, 2022). "In addition, administration of muscimol to microglia stimulated with lipopolysaccharide (LPS)/interferon-γ, the latter typically shows elevated levels following stroke significantly reduced the level of pro-inflammatory cytokines interleukin 6 (IL-6) and tumor necrosis factor alpha (TNFα)." (PMID 35401118, 2022). "However, some studies have shown that TNF-α levels remain unchanged after stroke." (PMID 36142524, 2022). "At the moment, DADA2 treatment may differ based on clinical phenotype: most inflammatory features can be effectively controlled using TNF inhibitors, with reduction of stroke recurrence, improvement of blood vessels endothelial integrity and resolution of inflammatory myeloid cell infiltrates." (PMID 35898506, 2022). "Thus there is a rationale for excessive cerebral TNF, and thus the same chronic symptoms, to persist, either when a pathogen is no longer present (e.g. long COVID and persistent Lyme disease), or is an irrelevancy (e.g. post‐stroke syndromes and TBI)." (PMID 35174650, 2022). "However, particular attention should be paid to salivary TNF-α, which may be a non-invasive biomarker of cognitive function/physical status in stroke subjects." (PMID 34433866, 2021). "Additionally, astrocyte and microglial activation may occur immediately after a stroke, amplified by multiple inflammatory factors, including tumor necrosis factor-α (TNF-α), interferon-γ (IFN-γ), interleukin-1β (IL-1β), IL-6, and adenosine triphosphate (ATP)." (PMID 34445248, 2021). "Moreover, both the TNF signaling pathway and the cytokine-cytokine receptor interaction were the two highly ranked pathways associated with stroke based on the results of KEGG analysis, indicating these pathways as crucial targets for the treatment of stroke." (PMID 34898370, 2021). "Importantly, depleting microglia induced a significant increase in the mRNA expression level of anti-inflammatory factors TGF-β1, Arg1, IL-10, IL-4, and Ym1 as well as a significant decline of pro-inflammatory factors TNF-α, iNOS, and IL-1β 3 days after stroke." (PMID 33757565, 2021). "To examine whether the protective effect of HIF-1α after stroke is achieved by modulating inflammation, we evaluated the expression levels and mRNA of pro-inflammatory cytokines (iNOS, TNF-α, NF-κB and p-IκBα/IκBα), and anti-inflammatory cytokines (IL-10) in the ischemic brain." (PMID 34205911, 2021).
Stroke (continued). "Increasing TNF-α levels in the stroke and penumbra areas facilitate the recruitment of circulating inflammatory cells that, once reached the injury site, get activated and in turn release TNF-α, thus promoting a vicious circle involving different pro-inflammatory cytokines." (PMID 33770265, 2021). "In our preclinical stroke model, we have previously shown that IL-1β and TNF are produced by largely segregated populations of microglia and macrophages after experimental stroke in mice, providing evidence of the functional heterogeneity among microglia and macrophages post-stroke." (PMID 32503645, 2020). "Experimental stroke studies which incorporate social isolation or social defeat stress have shown that both tissue and functional stroke outcome is affected by the increased expression of TNF-α and IL-6, increased glucocorticoid production, and suppression of the protooncogene bcl-2." (PMID 32477259, 2020). "Elevated levels of IL-6 and TNF-α in the spinal cord after stroke upregulate the concentrations of GAP-43 (growth-associated protein 43), NT-3 (neurotrophin-3), and BDNF, all of which are known to be involved in spinal axonal plasticity and lead to better spontaneous post-stroke recovery." (PMID 33042113, 2020). "Furthermore, there are premises suggesting value of some biomarkers in the diagnosis of specific stroke types, such as cardioembolic stroke (vWF, TNFα), hemorrhagic stroke (GFAP, MMP-9), large- and small-artery disease (IL-6; TNFα), or lacunar stroke (Glu, GABA)." (PMID 31701356, 2020). "We observed a significant enhancement of the cytokine-related genes such as TNF-α and iNOS and the downregulated gene TNF-β in ischemic mice after ki20227 treatment, indicating that these cytokine-related genes may be a risk factor after stroke." (PMID 33177990, 2020). "During neuroinflammation, induced by stroke or lipopolysaccharides, microglia are more sensitive to pathogens, or damage; they are thus initially activated into the M1 phenotype and produce common inflammatory signals such as IL-1 and TNF-α to trigger reactive astrocytes into the A1 phenotype." (PMID 32733433, 2020). "In addition, previous studies indicated that Prx1 could significantly induce the expression of TNF-α, IL-1β, and IL-6 via the Toll-like-receptor-4a-mediated NF-κB signaling pathway in stroke." (PMID 32317937, 2020). "In the literature, acupuncture enabled functional recovery in stroke patients through several mechanisms, such as brain reorganization, the regulation of neurochemical release in ischemic stroke patients, and the inhibition of TNF-α/NFκB expression in a rat model of hemorrhagic stroke." (PMID 32762664, 2020). "This association was independent of not only age and stroke severity, which are the most important stroke prognosticators, but also from circulating IL-6, a marker of systemic inflammation, and ex vivo release of TNFα, a marker of immunodepression." (PMID 32107751, 2020). "Compared with sham-operated mice, the productions of TNF-α (28.64 ± 3.03 versus 81.42 ± 8.73 pg/mg protein, P < 0.001; 28.48 ± 2.22 versus 57.99 ± 3.14 pg/mg protein, P < 0.001) were obviously increased in dMACO mice with saline treatment at days 14 and 21 after stroke." (PMID 31810470, 2019). "Tumour necrosis factor‐α signalling has been shown to participate in cerebral neuroinflammation after stroke; thus, the use of anti‐TNF‐α or recombinant TNF‐α to examine its role in stroke‐induced gut dysfunction in vivo may also impact brain infarct development." (PMID 31199577, 2019). "We hypothesized that the dramatic suppression of TNFα with clenbuterol treatment might be down-regulating the overall brain immune response to stroke at this sub-acute time point, so we also measured mRNA levels of another key pro-inflammatory mediator (iNOS) and an anti-inflammatory molecule (Ym1)." (PMID 31138227, 2019).